S100A8 (S100 calcium binding protein A8)
Diseases named in the same sentence as S100A8 in open-access papers (continued):
Sharing a sentence is not in itself a finding about the gene and the disease.
psoriasis (continued). "Notably, the “Role of IL-17A in Psoriasis” (T2, −log(FDR) = 1.67) pathway was enriched, in which downregulated CXCL3, IL-8, S100A8, S100A9, IL17RA and CXCL1 expression was observed." (PMID 29871627, 2018). "All other DEGPs could be placed along a continuum, with some showing greater psoriasis specificity (e.g., DBI, GLTP, HRNR, KRT73, ELOVL7), and others showing similar expression shifts in many or most skin diseases (e.g., MX1, S100A8, S100A9, STAT1, LAP3)." (PMID 26251673, 2015). "Moreover, S100A8/S100A9 are involved in interactions between keratinocytes and other immune cells and contribute to the pathogenesis of psoriasis by generating specific psoriatic milieu." (PMID 24901012, 2014). "Genes S100A8 and S100A9, frequently co-expressed and forming a heterodimer, belong to a multigenic and multifunctional family of calcium-binding proteins, that has been identified in several inflammatory skin conditions such as psoriasis, atopy, and cancer." (PMID 21556364, 2011). "Furthermore, S100A8 and S100A9 may inhibit psoriasis by prohibiting the synthesis of IL-17A and IL17-F." (PMID 40540498, 2025). "In addition, the expression of psoriasis-related inflammatory response markers, including Keratin 16, S100A8, and S100A9, was not reduced by anti-FGFR2IIIb treatment." (PMID 39919800, 2025). "S100A8/A9 is overexpressed in keratinocytes and innate immune cells, and their transcripts are significantly overexpressed in psoriasis lesions compared to non-lesional psoriasis or atopic dermatitis (AD) skin." (PMID 38256115, 2024). "Therefore, we explored whether S100A8 and S100A9 participate in the function of GSDME in keratinocytes for promoting psoriasis-like dermatitis." (PMID 38429278, 2024). "Interestingly, S100A8, S100A9 and S100A12 protein levels are used as sensitive biomarkers for monitoring disease activity in juvenile idiopathic arthritis, inflammatory bowel disease and psoriasis." (PMID 35055093, 2022). "However, the specific role of S100A8/S100A9 expression in keratinocytes during the process of psoriasis has never been addressed." (PMID 33643287, 2020). "Furthermore, IL-1β stimulation of NHEKs was found to induce upregulation of the mRNA and protein levels of pro-inflammatory cytokines, chemokines and antibiotic peptides including IL-36γ, CXCL1, CXCL2, CCL20, S100A7, S100A8 and S100A9, which are closely related to the pathogenesis of psoriasis." (PMID 32194991, 2020). "However, looking on the effects of cytokines highly relevant in the pathogenesis of psoriasis, i.e., IL-17A, IL-17F, IL-1α, or TNF, on S100A8 or S100A9 expression in keratinocytes we found strong effects on mRNA induction for both genes most pronounced for IL-17A > IL-17F > IL-1α > TNF." (PMID 33643287, 2020). "Twenty-one S100 proteins are known, of which S100A7 (psoriasin), S100A8 (calgranulin A), S100A9 (calgranulin B), S100A12 (calgranulin C), and S100A15 have antimicrobial effects and their expression levels are increased in the lesional skin and serum of psoriasis patients." (PMID 32947991, 2020). "Calgranulins S100A8 and S100A9 are markers of keratinocyte activation and have been demonstrated to play a role in hyper-proliferation and abnormal differentiation of keratinocytes in psoriasis and also result in the development of severe crusted lesions in sheep scab." (PMID 32886659, 2020). "S100A8 and S100A9, generally functioning as the S100A8/A9 heterocomplex, and S100A12 are implicated in non-infectious chronic inflammatory diseases such as RA, psoriasis and inflammatory bowel disease." (PMID 19284577, 2009). "After complement components and immunoglobulin chains, S100A8 was the first protein that, as an alarmin, plays a key role in the development of inflammation; moreover, it has been suggested that S100/S100A9 heterodimer may represent a good therapeutic target in psoriasis and psoriatic arthritis." (PMID 36700196, 2022).
psoriasis (continued). "Our data indicate that expression of S100A8 and S100A9 does not primarily influence maturation or activation of keratinocytes but rather represents the inflammatory response of these cells during psoriasis." (PMID 33643287, 2020). "By contrast, S100A8 and S100A9 proteins were abundant in skin tissues of all 15 psoriasis patients but not in tissues from any non-psoriasis control subject, suggesting that ANGPTL6 production and S100A8/S100A9 expression are not linked in the pathogenesis of psoriasis." (PMID 27698489, 2016).
Sepsis (109 papers, 2010 to 2026). Sepsis is defined as life-threatening organ dysfunction caused by a dysregulated host response to infection. "From a clinical perspective, the modulation of S100A8/A9 holds potential as a potent protective measure against sepsis in neonates, especially in preterm infants, who are at the highest risk of sepsis." (PMID 41591973, 2026). "Transcriptomic analyses of monocytes from 29 sepsis patients and 15 healthy donors revealed upregulated S100A8 and S100A9 expressions linked to MDSC recruitment." (PMID 40364841, 2025). "Our findings highlight the S100A8/A9-driven inflammatory cascade, its impact on immune cell interactions, and its potential as a diagnostic and prognostic biomarker in sepsis." (PMID 41303672, 2025). "We found that serum S100A8/A9 concentration at ICU admission is a significant predictor of 28-day mortality risk in sepsis patients." (PMID 40568710, 2025). "Serum S100A8/A9 concentration at ICU admission is a significant predictor of 28-day mortality risk in sepsis patients." (PMID 40568710, 2025). "Improving clinical outcomes and reducing the hyper-inflammatory response in sepsis can be achieved by targeting S100A8/A9 and the pathways that are linked to it." (PMID 41303672, 2025). "Studies by have also demonstrated that higher levels of S100A8/A9 in the bloodstream can serve as an early indicator of sepsis and predict a higher risk of ICU admission." (PMID 40568710, 2025). "Some studies have also found that S100A8 is an independent risk factor for poor prognosis in sepsis patients." (PMID 40356926, 2025). "This study aims to assess the clinical potential of S100A8/A9 and resistin as novel biomarkers for predicting mortality risk in sepsis patients." (PMID 40568710, 2025). "The study demonstrated a strong association between elevated plasma levels of S100A8/A9 and the severity of left ventricular dysfunction in patients with sepsis." (PMID 40948795, 2025). "Recently, S100A8/A9 has emerged as a promising biomarker for sepsis, and it is a pathogenic molecule with both pro-inflammatory and immunosuppressive properties, primarily found in myeloid cells, including neutrophils and monocytes." (PMID 40568710, 2025). "Elevated S100A8/A9 is associated with the development of LV dysfunction in severe sepsis patients and in a mouse model of endotoxemia." (PMID 37773186, 2023). "Multiple studies have shown that S100A8/A9 are upregulated in the circulation of animals and patients with sepsis, and that their levels are associated with disease severity." (PMID 36768433, 2023). "The diagnostic and prognostic accuracy of MMP8 and S100A8 was evaluated using clinical peripheral blood samples, CSF, and behavioral experiments in a rat model of sepsis." (PMID 37901226, 2023). "The influence of S100A8/A9 on the inflammation to gain further insights into the underlying mechanisms of sepsis-induced lung injury was investigated." (PMID 37978525, 2023). "We show that elevated plasma S100A8/A9 levels are associated with systolic LV dysfunction in patients with severe sepsis admitted to the ICU." (PMID 37773186, 2023). "In sepsis patients, elevated plasma S100A8/A9 was associated with left-ventricular (LV) systolic dysfunction and increased SOFA score." (PMID 37773186, 2023). "Exhausted monocytes treated with high-dose LPS express pathogenic mediators such as S100A8, independently identified in monocytes from patients suffering from sepsis or COVID-19168–170." (PMID 35091696, 2022). "In human sepsis and septic shock, S100A8/A9 was proposed as a diagnostic and prognostic marker, and the potential role as a therapeutic target is still a topic of ongoing research." (PMID 33574730, 2021). "Preterm infants had generally lower levels of S100A8/A9 in cord blood than term infants and low levels within the preterm group were associated with an increased risk for sepsis." (PMID 32612607, 2020).
Sepsis (continued). "In human neonates, S100A8/A9 serum levels were negatively associated with the risk of sepsis and significantly higher in term compared to preterm infants." (PMID 32425933, 2020). "In preterm infants, lower S100A8/A9 protein levels are associated with an increased risk for late onset sepsis, while another study shows that HCA and FIRS are associated with a decreased risk for late onset sepsis in preterm infants." (PMID 32612607, 2020). "Low S100A8/A9 protein levels in cord blood are also associated with an increased risk of late onset sepsis in preterm infants." (PMID 32612607, 2020). "The profound immaturity of cell-autonomous regulation together with the impaired age-specific alternative kind of regulation by S100A8/A9 provided an explanation for the massively increased sepsis risk of individual preterm infants." (PMID 32425933, 2020). "To analyze whether the timing-dependent differential effects of aCS on the infants’ sepsis risk might be related to S100A8/A9 we determined the serum levels of S100A8/A9 during the first three days of life in the different aCS treatment groups." (PMID 41591973, 2026). "SRSF7, E2F2, RAB13, and S100A8 were identified as potential pathogenic biomarkers of sepsis." (PMID 40909263, 2025). "Additionally, we measured the serum levels of S100A8/A9 and resistin only on the first day of admission and assessed their association with short-term sepsis mortality risk." (PMID 40568710, 2025). "This association suggests that S100A8/A9 may play a direct role in the inflammatory response associated with sepsis." (PMID 40948795, 2025). "This could provide a plausible explanation for the higher risk of death observed in sepsis patients with relatively low S100A8/A9 levels at hospital admission compared to those who survived." (PMID 40568710, 2025). "Similarly, deficiency or inhibition of S100A8/A9 in mice conferred protection against lung injury development in endotoxin-induced sepsis and improve the survival." (PMID 39686985, 2024). "Similarly, the involvement of S100a8/a9 in the mechanisms underlying sepsis-induced cardiomyopathy (SIC) is evident, likely through its activation of TLR4-ERK1/2-Drp1-dependent mitochondrial fission and impairment." (PMID 39267971, 2024). "Additionally, the diagnostic value of S100A8/A9 in sepsis was assessed using receiver operating characteristic." (PMID 37978525, 2023). "In addition, we confirmed the role of the neutrophil-associated protein S100A8 in the early warning and treatment of severe burn-associated sepsis." (PMID 36659877, 2023). "Taken together, these data indicate that S100A8/A9 might have a causal effect in the development of severe sepsis and might be therapeutically targeted to ameliorate disease severity." (PMID 37773186, 2023). "In addition, we identified S100A8 as a key target for early warning and treatment of burn-associated sepsis on the basis of proteomics and neutrophil single-cell transcriptomics." (PMID 36659877, 2023). "In severe burn-associated sepsis, the protein S100A8 has both warning and therapeutic effects." (PMID 36659877, 2023). "However, limited knowledge exists concerning the biological role of S100A8/A9 in pulmonary vascular endothelial barrier dysfunction, as well as the diagnostic value of S100A8/A9 in sepsis." (PMID 37978525, 2023). "Moreover, the clinic diagnostic value of S100A8/A9 in sepsis was assessed using receiver operating characteristic." (PMID 37978525, 2023). "Elevated plasma S100A8/9 in sepsis patients is associated with increased risk for mortality." (PMID 35945238, 2022). "Recently, transcriptomic analyses of MKs in COVID-19 and sepsis in general have highlighted the overexpression of two S100A8/S100A9 genes encoding two proinflammatory myeloid-related proteins (MRP8/14), also called calprotectin proteins, which are found in granules." (PMID 35563812, 2022).
Sepsis (continued). "Our data suggest that leptin-induced S100A9 overexpression exerts beneficial actions; yet, this idea is at odds with the fact that S100A9 forms a complex with S100A8, namely calprotectin, that has been shown to exert several deleterious effects including underlying sepsis-induced lethality." (PMID 31391467, 2019). "In addition, low expression of S100A8/A9 in neonatal serum was associated with enhanced susceptibility toward sepsis." (PMID 30976008, 2019). "Recent research has demonstrated that the S100A8/A9-NETosis feedback loop is considered a central regulator of sepsis." (PMID 42079585, 2026). "This review systematically proposes the S100A8/A9-NETosis positive feedback loop as a core pathological mechanism and explores its potential pathways in sepsis." (PMID 42079585, 2026). "The findings of this study suggest that T0 attenuates sepsis-induced pulmonary injury by promoting macrophage autophagy via suppression of S100A8 expression." (PMID 40994643, 2025). "Excessive S100A8/A9 production drives a positive feedback loop, worsening sepsis-induced hyperinflammation and increasing mortality." (PMID 40761792, 2025). "And according to survival curve analysis, patients with low serum S100A8/A9 admission levels in sepsis had lower survival rates than those with high serum S100A8/A9 admission levels." (PMID 40568710, 2025). "On the day of admission, elevated serum concentrations of S100A8/A9 were observed in patients with sepsis." (PMID 40568710, 2025). "The S100A8/A9 heterodimer, predominantly expressed in neutrophils and monocytes, emerges as a key immunosuppressive mediator in sepsis via impairing DCs maturation and promotes MDSCs accumulation." (PMID 40364841, 2025). "During sepsis, the S100A8/A9 complex activates the classical Toll-like receptor 4 (TLR4) signaling pathway in monocytes, inducing the expression of pro-inflammatory mediators related to NF-κB, and can be released as a DAMP." (PMID 40568710, 2025). "Among these 141 sepsis patients, serum S100A8/A9 concentrations were considerably elevated in those with non-shock sepsis (84 cases) relative to those with septic shock (P < 0.0001)." (PMID 40568710, 2025). "Then, four diagnostic genes of sepsis (LTF, MMP9, S100A9, and S100A8) and two diagnostic genes of relapsed B-ALL (LTF and MMP9) were screened by SVM-RFE, respectively." (PMID 41007866, 2025). "RT-qPCR revealed decreased SRSF7 expression and increased RAB13, E2F2, and S100A8 expression in sepsis." (PMID 40909263, 2025). "In contrast, S100A8/A9 and resistin as sepsis biomarkers not only aids in diagnosing sepsis but also distinguishes between severe sepsis, G- and G+ infections, and different immune subtypes of sepsis patients." (PMID 40568710, 2025). "This work examines the activation of the IL-17 pathway induced by S100A8/A9, emphasizing its pro-inflammatory function in sepsis and multi-organ failure." (PMID 41303672, 2025). "Given its critical role in sepsis, targeting S100A8/A9-TLR4/RAGE signaling presents a potential therapeutic strategy to disrupt the IL-17-driven inflammatory cascade." (PMID 41303672, 2025). "Collectively, our findings delineate a novel LXRα/S100A8 pathway that can be therapeutically targeted to mitigate sepsis-induced lung injury." (PMID 40994643, 2025). "They found that plasma S100A8/A9 levels were significantly elevated in severe sepsis patients and correlated with left ventricular systolic dysfunction and higher SOFA scores." (PMID 41293242, 2025). "To further explore the clinical relationship between LXRα and S100A8 expression in sepsis-induced ALI, we conducted a bioinformatics analysis and found an inverse correlation." (PMID 40994643, 2025). "During sepsis, dysregulated pyroptosis leads to substantial S100A8/A9 release, exacerbating the inflammatory response and inducing platelet pyroptosis." (PMID 40568710, 2025).